RN7SL253P (RNA, 7SL, cytoplasmic 253, pseudogene)
Gene: Miscellaneous RNA gene on chromosome 4 (173,141,643 to 173,141,938, forward strand). Ensembl gene ENSG00000241652.
Homologues: Orthologues: chimpanzee Metazoa_SRP (99% identical), macaque Metazoa_SRP (88% identical). Paralogues in human: RN7SL1 (84% identical), RN7SL2 (84% identical), RN7SL3 (83% identical), RN7SL126P (81% identical), RN7SL451P (81% identical), RN7SL45P (81% identical), RN7SL664P (81% identical), RN7SL679P (81% identical), RN7SL769P (80% identical), RN7SL230P (80% identical), RN7SL186P (80% identical), RN7SL49P (80% identical), and 700 more.